CEACAM1 (CEA cell adhesion molecule 1)
Diseases named in the same sentence as CEACAM1 in open-access papers (continued):
Sharing a sentence is not in itself a finding about the gene and the disease.
cancer (136 papers, 2006 to 2026). A tumor composed of atypical neoplastic, often pleomorphic cells that invade other tissues. "Carcinoembryonic antigen cell adhesion molecule 1 (CEACAM1) plays an important role in regulating immune responses associated with infection, inflammation, and cancer." (PMID 38243323, 2024). "Pro-inflammatory cytokines and CEACAM1 have been implicated in the modulation of cellular functions and signaling pathways, contributing to the expression of critical mediators in cancer and inflammation." (PMID 37691945, 2023). "Our data thus established a functional role for NET-associated CEACAM1 in cancer, leading to renewed interest over its potential influence on response to therapy as well." (PMID 35267667, 2022). "A pluripotent oncogene known as Metadherin (MTDH, also known as AEG-1), which has been implicated in driving cancer metastasis, can directly interact with CEACAM1." (PMID 36497444, 2022). "TIM-3 and CEACAM1 co-expression was thus associated with an immunosuppressive TME conducive to cancer progression and therapy resistance." (PMID 35267667, 2022). "While recent works have focused on the immunomodulatory and immunosuppressive consequences of CEACAM-1 engagement by Fn in T and NK cells, the data presented here underscore the relevance of this pathogenic interaction on the cancer cell side." (PMID 36139097, 2022). "The results showed that the CEACAM1+ TILs count was positively associated with the CEACAM1 expression level in cancer tissues (r = 0.413, p<0.001)." (PMID 34368221, 2021). "CEACAM1 is associated with various cancers, and its expression level and function is different among them." (PMID 31481751, 2019). "Unpublished truncating variants in two genes under-expressed in cancer [CEACAM1:c.553_554insAGGC; p.(Leu185Glnfs∗26), and MIB2: c.153C > A; p.(Cys51∗)] were also inherited." (PMID 30233642, 2018). "Blockade of the CEACAM1 signaling pathway has recently been implicated as a novel mechanism for cancer immunotherapy." (PMID 30349641, 2018). "To assess the potential of CEACAM1 as a diagnostic biomarker to distinguish advanced cancer patients (IIB/III) from early clinical stages (IIA), we got an AUC of 0.83 (95%CI 0.74–0.92) with a sensitivity of 0.85 and a specificity of 0.74." (PMID 27074014, 2016). "Survival analysis revealed that both neutrophils infiltration and CEACAM1 overexpression were associated with poorer cancer-related survival of TSCC patients (P<0.05), and neutrophils infiltration was an independent prognostic factor for TSCC (P<0.05)." (PMID 24587171, 2014). "For example, Carcinoembryonic antigen-related cell adhesion molecule 1 (CEACAM-1) has recently been reported to be implicated in cancer development and progression." (PMID 19216806, 2009). "Despite its well-known association with cancer less is known about CEACAM1-dependent mechanisms that might affect cancer biology." (PMID 38077351, 2023). "Therefore, to analyze the relation of cause and effect between CEACAM1 and cancer and the underlying signaling in pre-clinical cancer models is a prerequisite for a later transition of experimental findings into clinical applications." (PMID 38077351, 2023). "This could be due to the cancer-associated pro-inflammatory milieu that might promote CEACAM1 expression." (PMID 38077351, 2023). "Furthermore, later clinical association studies indicate that CEACAM1 expression seems more likely to be associated with cancer progression and poor prognosis in most cancer entities." (PMID 38077351, 2023). "CEACAM1 is an extensively studied cell surface molecule with established functions in modulating the immune responses associated with infection, inflammation, and cancer." (PMID 34908921, 2021). "Although in recent years the potential value of CEACAM1 as a clinically highly relevant diagnostic and therapeutic target for various malignant diseases has gained increasing attention, its role in different cancer entities appeared rather complex." (PMID 30871206, 2019).
cancer (continued). "CEACAM1 is associated with malignant potential of various cancers." (PMID 31481751, 2019). "We speculated that the correlation between CEACAM1 expression and neutrophils infiltration may represent another cause for the poor clinical outcomes of CEACAM1 overexpression in cancers." (PMID 24587171, 2014). "To determine whether altered splicing of CEACAM1 is linked to tumorigenesis, we examined the splicing profile of CEACAM1 transcripts in a variety of human cancer cell lines derived from brain, breast, colon and prostate." (PMID 18507857, 2008). "Therefore, cell lines derived from these tissues should serve as model system for assessing whether altered CEACAM1 splicing is associated with cancer." (PMID 18507857, 2008). "Carcinoembryonic antigen-related cell adhesion molecule 1 (CEACAM1) is a multifunctional immunomodulatory protein involved in both immune activation and immune suppression across diverse cancer types." (PMID 42077470, 2026). "For instance, CEACAM1 binds to F. nucleatum via the trimeric autotransporter adhesin CbpF, inhibit T-cell response, support immune evasion of cancer cells, and promote tumorigenesis." (PMID 40311681, 2025). "They further underscore Gal-9 monotherapy or combined treatment regimens targeting additional Gal-9 axis components, TIM-3, CEACAM1, and/or PD-1, and other pathways as potentially synergistic approaches to cancer therapy." (PMID 40869319, 2025). "Remarkably, the group of cancer-related proteins,i.e., CEACAM1,CEACAM5, and CEACAM6 as well as the minichromosome maintenance complexcomponents MCM3, MCM4, and MCM6 showed clear protein abundance patternsrelated to the radiation response." (PMID 40574313, 2025). "DIA 12.3 had high binding to an N-terminal fragment of CEACAM1 (N+A1 domains) in an ELISA and to a number of cancer cell lines known to express CEACAM1." (PMID 38346003, 2024). "A potential cancer-related immunomodulatory action of Anisakis EVs also emerged with reduction in CEACAM-1 protein (P = 0.01), which mediates angiogenesis, inflammation and innate and adaptive immune responses." (PMID 39285481, 2024). "CEACAM1 has been shown to be aberrantly expressed in a variety of tumors, and modulation of CEACAM1-related signaling pathways has been suggested as a novel approach for cancer immunotherapy in recent years." (PMID 36712923, 2023). "An interesting ligand expressed in cancer tuft cells is CEACAM1 which can modulate and inhibit responses of several immune cell types such as Natural Killer (NK) or T cells." (PMID 37386128, 2023). "In this review, we summarize pre-clinical and clinical evidence linking CEACAM1 to tumorigenicity and cancer progression." (PMID 38077351, 2023). "On the other hand, CEACAM1 was found to be pro-angiogenic in vivo and to stimulate cellular metastasis in various cancer types." (PMID 37313172, 2023). "Similar studies investigating the impact of CEACAM1 on apoptosis in cancer cells that include signaling pathway analysis are limited." (PMID 38077351, 2023). "Antibody-mediated inhibition of CEACAM1 in head and neck squamous cell carcinoma cells enhances NK cell anti-cancer activity in vitro." (PMID 38077351, 2023). "For that purpose, in this review we will I) summarize the clinical data on CEACAM1 and cancer progression and survival, II) give an overview of potential underlying mechanisms and III) highlight current therapeutic approaches and bottlenecks." (PMID 38077351, 2023). "CEACAM1 has been reported to mediate antitumor effects in vivo, and targeting the CEACAM1-related signaling pathway has recently been considered as a new approach for cancer immunotherapy." (PMID 36712923, 2023). "ITIMs on CEACAM1-L bind to other extracellular ligands, including other CEACAM family members and CEACAM1, suppressing immune cells and allowing immune evasion by cancer cells." (PMID 36741860, 2023). "For instance CEACAM1 affects anti-cancer immune reactions by modulating the function of natural killer cells and T-cells." (PMID 38077351, 2023).
cancer (continued). "In coordination with CEACAM1s ability to downregulate immune cells, CEACAM5 is a binding partner to CEACAM1 that can elicit this signaling, allowing for immune evasion by cancer cells." (PMID 36741860, 2023). "Monoclonal antibodies targeting CEACAM1 have been approved for the treatment of advanced and recurrent cancers in clinical trials." (PMID 37575253, 2023). "In order to confirm that the observed Ras-mediated transcriptional activation translates into CEACAM1 expression on the surface of cancer cells, we performed FACS analyses on cells dissociated from the liver and peritoneal tumours." (PMID 36656749, 2023). "Based on CEACAM1 upregulation, anti-CEACAM1 antibodies are suggested to mark cancer cells for immune cell-based killing." (PMID 38077351, 2023). "Since CEACAM1 has a robust inhibitory effect on NK-mediated cancer cell killing, cancer immunotherapy strategies targeting this protein have been considered." (PMID 37108808, 2023). "Our glycoproteomic results indicated that 2DG led to the changes in N-glycosylation of some well-known cancer-associated glycoproteins, including LGALS3BP, CEACAM1, and EGFR." (PMID 35897829, 2022). "Previous studies reported that TILs express high levels of CEACAM1 and produce obviously less IFN-γ compared with T cells derived from para-cancer tissue, suggesting a substantial role of CEACAM1 in mediating T cell exhaustion." (PMID 35800370, 2022). "CD200 (OX-2) and carcinoembryonic antigen-related cell adhesion molecules (CEACAM-1), the cell surface tolerance signals exist commonly between trophoblasts and cancer cells." (PMID 35517798, 2022). "Mechanistically, β‐catenin upregulates cancer cell surface metadherin, which communicates through CEACAM1 expressed on macrophages to produce CCL3." (PMID 35403834, 2022). "The genes observed in this network (CEACAM1, IGF1, MET, MMP1, MMP3 and WNT5A) were upregulated in cSII/III and are known to be linked to invasive properties in several other cancer types." (PMID 35022523, 2022). "Adding antibodies specific for two of these molecules, Annexin-A1 and CEACAM1, inhibited macrophage activation, supporting their role as cancer “danger signals” recognized by macrophages." (PMID 34712237, 2021). "CEACAM1 is an extensively studied cell surface molecule with established functions in multiple cancer types, as well as in various compartments of the immune system and plays a dual role in different cancers." (PMID 34908921, 2021). "CEACAM1 expression in T-cells, NK-cells, B-cells, monocytes and granulocytes is important for the progression and development of various types of cancer." (PMID 34943606, 2021). "TIM-3+ TILs count demonstrated a significantly positive correlation with the expression of CEACAM1 in cancer cells (r = 0.350, p = 0.001)." (PMID 34368221, 2021). "Since F. nucleatum is maintained in distant metastases of CRC, it will be of interest to investigate the impact of the interaction between F. nucleatum CbpF and CEACAM1-positive cancer cells on both cancer cell proliferation and metastasis." (PMID 34336716, 2021). "CEACAM1 was described to be downregulated or overexpressed in numerous tumors, and it has been considered as a promising candidate biomarker for some cancers." (PMID 34368221, 2021). "Meanwhile, according to our results, CEACAM1 expression was higher in poorly differentiated carcinomas compared with well differentiated ones, which implies its correlation with unfavorable prognosis." (PMID 34368221, 2021). "Further analysis showed CEACAM1 expression on carcinoma cells was an independent prognostic factors for both OS and DFS." (PMID 34368221, 2021). "This protein was recently shown to bind carcinoembryonic antigen-related cell adhesion molecules (CEACAMs) including CEACAM1, an inhibitory receptor expressed mainly by activated T and NK cells and involved in cancer development and progression." (PMID 32872465, 2020).
cancer (continued). "Lower plasma levels were found for ITGAV and CEACAM1 in patients with cancer compared to patients with benign tumors." (PMID 33075095, 2020). "A six-biomarker model (HE4, CA125, CXCL1, ITGAV, CEACAM1, IL-10RB and age) was the best model for discrimination between benign tumors and borderline tumors + cancer, with AUC 0.868 and sensitivity 0.86 / specificity 0.82 at best point cut-off (p = 0.016)." (PMID 33075095, 2020). "In more advanced stages, CEACAM1 expression and cytoplasmic domain isoform balance are involved in promoting motility and invasion of cancer cells." (PMID 31481751, 2019). "Previous studies have shown that deletion of carcinoembryonic antigen-related cell adhesion molecule 1 (CEACAM1) gene can contribute to cancer progression." (PMID 31480483, 2019). "In the background that cancer cells basically express CEACAM1, cancer cells modulate CEACAM1 cytoplasmic domain dominance, leading to promotion of malignant phenotypes such as motility, invasion, metastasis and prognosis." (PMID 31481751, 2019). "CEACAM1 is a member of CECAM family in various cells derived from normal tissues or malignant tumors." (PMID 31072323, 2019). "CEACAM1 is more sensitive and specific than the already consecrated CA 19-9 in differentiating cancer from normal controls, and this is improved by combining CEACAM1 and CA 19-9." (PMID 30406153, 2018). "In the context of cancer, there are contradictory reports describing CEACAM1 as an activator or repressor of the immune response." (PMID 30050594, 2018). "The decreased expression of CEACAM1 in early malignancies and its upregulation in advanced cancers were difficult to reconcile." (PMID 30406153, 2018). "CEACAM1 appears to be a valuable prognostic factor in various tumors through its different expression patterns on cancer cells." (PMID 30406153, 2018). "These well-defined inhibitory roles of CEACAM1 in T and NK cells present the molecule as a valuable target for cancer immunotherapy with monoclonal antibodies in late-stage cancer." (PMID 30406153, 2018). "In general, dysregulation of CEACAM1 expression is frequently observed during malignant progression and invasion of various carcinomas." (PMID 30314283, 2018). "The expression of CEACAM1 mediates intercellular protein interactions and intracellular signaling during inflammation, microbial and viral infection, angiogenesis, cancer progression, and metastasis." (PMID 27642217, 2016). "Beyond its prognostic value in cancers, CEACAM1 has often been referred to as a marker for tissue differentiation, especially in the context of mammary gland differentiation and mammary epithelial lumen formation." (PMID 27572314, 2016). "Distant metastases and chemotherapeutic response were the most important and accurate prognostic determinants and we noted that these were positively correlated to CEACAM1, which was usually a late-cancer finding." (PMID 27074014, 2016). "Even though the exact molecular mechanism remains to be deciphered, our data identify CEACAM1 as a gatekeeper in EMT that provides novel insights into the regulation of cancer invasion and metastasis." (PMID 27572314, 2016). "The present report clearly points towards an involvement of CEACAM1 in the regulation of the EMT-phenotype of tumor cells through Wnt/β-catenin pathway which impacts on cancer progression and metastasis." (PMID 27572314, 2016). "Reviewing the literature we have brought into focus a key molecule, CEACAM1, as one of the latest hallmarks of cancer involved in the main mechanisms responsible for increasing the invasiveness of melanocytes." (PMID 27642217, 2016). "The relationship of CEACAM1 expression and neutrophils density with clinicopathologic parameters and cancer-related survival of TSCC patients were evaluated." (PMID 24587171, 2014). "Our result showed that CEACAM1 expression in cancer tissues was higher than peritumoral eptithelial tissues." (PMID 24587171, 2014).
cancer (continued). "Although the published literature on CEACAM1 expression in cancer is contradictory, most investigators agree that these changes in expression offer an important indicator for clinical diagnoses." (PMID 23885995, 2013). "CEACAM1, one of the binding partners of CEACAM5 in the CEACAM family, has been implicated in contact-dependent regulation of immune response associated with cancer." (PMID 21731662, 2011). "We were particularly interested in identifying proteins acting as repressors of CEACAM1 transcription, since CEACAM1 mRNA levels are downregulated in many cancer types." (PMID 21050451, 2010). "Several studies have reported down-regulation of CEACAM1 expression in cancers of epithelial origin, including colon, breast, liver, gastric and prostate." (PMID 21050451, 2010). "CEACAM1 is also expressed on the luminal surface of prostate glands, and like its expression in the mammary gland, is down-regulated in cancer." (PMID 20404914, 2010). "Changes in the isoform ratios of CEACAM1 favoring the S form has already been demonstrated to increase proliferation in cancer cells." (PMID 20090913, 2010). "Additionally, modulation of carcinoembryonic antigen-related cell adhesion molecule 1 (CEACAM1) signaling has been proposed as a novel approach in cancer immunotherapy." (PMID 40963620, 2025). "Moreover, CEACAM1 functions as an inhibitory receptor on NK cells, enhancing cancer cells' ability to avoid immune surveillance." (PMID 41233805, 2025). "Moreover, in the transwell experiment, we similarly found that the number of invasive cancer cells in BC cells overexpressing CEACAM1-3L and 4L was also significantly less than that in the blank and NC groups." (PMID 39513107, 2024). "Based on pre-clinical data CEACAM1-specific antibodies were proposed for anti-cancer therapy." (PMID 38077351, 2023). "suggests that CEACAM1 expression in microvesicles derived from cancer cells might influence cancer signaling on other cells including endothelial cells." (PMID 38077351, 2023). "It has also been shown that CEACAM1 can regulate the activation induced inhibitory molecule-3 (Tim-3) of T cell immunoglobulin domain and mucin domains involved in tolerance and shown to induce T cell exhaustion in chronic viral infections and cancer." (PMID 37589542, 2023). "Having such data for other cancer entities too might help to explain divergent results concerning cancer stage-related CEACAM1 expression and patient survival." (PMID 38077351, 2023). "However, cumulative evidence from pre-clinical as well as clinical data suggests a more complex influence of CEACAM1 on cancer biology." (PMID 38077351, 2023). "The impact of CEACAM1 on B cells in cancer is still contradictory discussed." (PMID 38077351, 2023). "Finally, since CEACAM1 expression in cancer tissue usually exceeds that in the surrounding healthy tissue by far, anti-CEACAM1 antibodies were suggested to be used in surgery to identify cancer tissues in order to enable complete cancer resection." (PMID 38077351, 2023). "Since CEACAM1 affects the activation of T cells, B cells and NK cells in the context of cancer, it might be a promising target." (PMID 38077351, 2023). "Several studies investigated the potential impact of CEACAM1 on cancer in human specimen." (PMID 38077351, 2023). "One of the first hints that CEACAM1 might support cellular survival by decreasing apoptosis came from studies investigating non-cancer cells like granulocytes and monocytes." (PMID 38077351, 2023). "However, beside cancer cells a variety of cells express CEACAM1 depending on activation state and age." (PMID 38077351, 2023). "The expression level of CEACAM1 mRNA was analyzed in different cancer types." (PMID 36712923, 2023). "CEACAM1 was shown to be a prognostic marker in patients suffering from cancer." (PMID 38077351, 2023). "Besides, a recent study suggests that macrophage-cancer cell interaction via CEACAM1 promotes cancer metastasis." (PMID 38077351, 2023).